BRCA2 (BRCA2 DNA repair associated)
Diseases named in the same sentence as BRCA2 in open-access papers (continued):
Sharing a sentence is not in itself a finding about the gene and the disease.
prostate carcinoma (continued). "The presence of prostate cancer was significantly higher in BRCA2 compared to BRCA1 patients or wild type patients (p < 0.05)." (PMID 29884136, 2018). "In advanced prostate cancer, recently reported BRCA mutation rates, assessed by whole genome sequencing, were 0.6% for BRCA1 and 12% for BRCA2; in all cases biallelic inactivation was present." (PMID 30518089, 2018). "Among the 421 male participants, 2.9% of BRCA1 PV carriers and 6.2% of BRCA2 PV carriers were diagnosed with prostate cancer at inclusion (mean age at diagnosis for BRCA1: 61.5, range 48–71 and 64.1, range 50–78 for BRCA2)." (PMID 30430080, 2018). "Prostate cancer was the most commonly diagnosed cancer, seen in 13 patients, 11 of whom were BRCA2 positive." (PMID 29433453, 2018). "Previously, it has been demonstrated that PCAT-1 expression in prostate cancer cells leads to a functional insufficiency in homologous recombination through its inhibitory effect on the BRCA2 tumor suppressor." (PMID 28989584, 2017). "Excluding skin cancer, only the BRCA2/ATM pathogenic variant carrier reported multiple primary cancers (MBC and prostate cancer)." (PMID 28008555, 2017). "Here we describe a case in which the application of WGS identified a tumoral BRCA2 deletion in a patient with aggressive dedifferentiated prostate cancer that was repeat-biopsied after disease progression." (PMID 28487881, 2017). "Tumors with mutations in genes involving homologous recombination such as BRCA2 are sensitive to PARP inhibition, with a recent phase II study demonstrating biochemical, radiological, and survival benefits in patients with BRCA2-mutant prostate cancer." (PMID 28487881, 2017). "While the small sample size is a limitation of this study, it underscores the role of BRCA2 not only in the progression prostate cancer but also in the response to one of the current standard therapies." (PMID 28676659, 2017). "Therefore, the use of BRCA2 mutation as a clinical prognostic factor could help stratify the high-risk patients and provide clinical strategies for more effective targeted treatments for patients with prostate cancer." (PMID 28410213, 2017). "In a study of aggressive, treatment-naïve advanced prostate cancer assessing BRCA1/2 mutations by whole genome sequencing, a 0.6% BRCA1 and 12% BRCA2 mutation rate was observed, all with biallelic inactivation, and half of which were somatic mutations." (PMID 28525389, 2017). "Inherited genetic conditions have also been associated with prostate cancer, for an elevated risk of prostate cancer has been noted in men with Lynch syndrome and men that carry BRCA1 and BRCA2 gene mutations." (PMID 29181019, 2017). "(iii) One male patient, who carried a frameshift insertion (rs80359499) in BRCA2, had prostate cancer in his early-70’s and died a few years later." (PMID 27930734, 2016). "BRCA2-driven prostate cancers demonstrate good response to platinum-containing therapy and PARP inhibitors." (PMID 27555886, 2016). "The BRCA1 and BRCA2 genes, whose best known function is concerned with the DNA damage response, have been reported to contribute to prostate cancer, although to different extents." (PMID 26433958, 2015). "Mutations in BRCA1, BRCA2, BRIP1/FANCCJ, CHEK2, MMR, and NBS1 have been found to confer an increased risk of prostate cancer." (PMID 26433958, 2015). "Furthermore, by studying prostate tissue specimens from prostate cancer patients a direct correlation between presence of mtDNA large deletions and loss of BRCA2 protein in vivo was found, suggesting that mtDNA status might serve as a marker to predict therapeutic efficacy to PARP inhibitors." (PMID 25136623, 2014). "Constitutive activation of MAPK/ERK signaling inhibits proliferation of prostate cancer cells via upregulation of BRCA2." (PMID 24349321, 2013).
prostate carcinoma (continued). "For prostate cancer, the SIR was substantially elevated overall (6.54; 95% CI 3.71–11.51; P<0.001) and within subgroups defined by BRCA2 mutation carrier and testing status (all P<0.001)." (PMID 20877337, 2010). "This suggests that BRCA2-driven prostate cancer would initially respond to conventional androgen ablation." (PMID 20585617, 2010). "This suggests human BRCA2 mutant prostate tumours, like the majority of prostate cancers, will respond to hormone therapy, but will relapse, as frequently occurs in this disease." (PMID 20585617, 2010). "We have undertaken a genetic analysis of Brca2 function in the adult mouse prostate to define its role in prostate cancer and to create an in vivo model of Brca2-dependent prostate disease progression." (PMID 20585617, 2010). "However, the role of BRCA2 in high risk prostate cancer pedigrees remains unclear." (PMID 19476645, 2009). "Although the increase in risk of developing breast, ovarian, and prostate cancer in BRCA1 and BRCA2 mutation carriers has been studied extensively, its impact on mortality is not well quantified." (PMID 19277124, 2009). "In this study, we compared survival of men with a BRCA2 mutation and prostate cancer with that of men with a BRCA1 mutation and prostate cancer." (PMID 18577985, 2008). "Prostate cancer incidence has been shown to be higher in BRCA1 and BRCA2 mutation carriers under the age of 65 years." (PMID 18182994, 2008). "The increased incidence of prostate cancer is interesting in view of involvement of BRCA2/FANCD1 in the FA gene pathway; male BRCA2 carriers have an increased risk of prostate cancer so there is a theoretical molecular link." (PMID 18786261, 2008). "To address this issue, we plan to identify the BRCA2 carriers among a large sample of prostate cancer patients and to characterise them in terms of clinical presentation, pathology and response to treatment." (PMID 18577985, 2008). "Intriguingly, two genes (BCCIP, HMG20B) appeared in our analysis that interact with BRCA2, another, albeit weaker candidate for a hereditary prostate cancer gene." (PMID 17280610, 2007). "Our findings indicate that genistein upregulates BRCA1 and BRCA2 expression in breast and prostate cancer cell lines." (PMID 16434996, 2006). "Here, we tested the effect of I3C on BRCA1 and BRCA2 expression in breast and prostate cancer cells." (PMID 16434996, 2006). "Time course studies of prostate cancer cell lines showed a delay in the induction of BRCA2 by I3C (first observed at 6 h) relative to that of BRCA1 (1 h)." (PMID 16434996, 2006). "However, the impact on prostate cancer is lower than that of BRCA2, and their impact on aggressiveness is also unclear." (PMID 41423785, 2026). "The discovery of a pathogenic BRCA2 mutation enabled the consideration of PARP inhibitor‐based combination therapy, emphasizing the critical role of molecular diagnostics in guiding individualized treatment for rare prostate cancer subtypes." (PMID 41472903, 2026). "Also, BRCA2 prostate cancer patients were more frequently diagnosed with other cancers, with male breast cancer being the most frequent (32%)." (PMID 41970070, 2026). "In this study, BRCA1 carriers were significantly associated with aggressive prostate cancer, and each category tended to be worse than noncarriers, suggesting a similar trend to BRCA2 carriers." (PMID 41423785, 2026). "Consequently, detecting CNV deletions of exon 22 in BRCA1 and exon 27 in BRCA2 is critical for guiding therapeutic strategies for advanced prostate cancer." (PMID 40725150, 2025). "While EI_1080 has three deceased relatives with GC that were not tested for variants, his brother who was diagnosed with prostate cancer carries the BRCA2 c.156_157insAlu variant." (PMID 40446793, 2025).
prostate carcinoma (continued). "At the gene level, our case-control collapsing analysis confirms associations between rare damaging variants in four genes and increased prostate cancer risk: SAMHD1, BRCA2 and ATM at the study-wide significance level (P < 1×10−8), and CHEK2 at the suggestive threshold (P < 2.6×10−6)." (PMID 39971927, 2025). "Importantly, several studies also suggested that PGS can modify the penetrance of BRCA2 PV carriers for several cancers, including breast and prostate cancer." (PMID 40462315, 2025). "This study examines the mutations in BRCA2 and HOXB13 which are some of the best described genes associated with hereditary prostate cancer, emphasizing the rationale of why RFLP could aid in the early diagnosis of patients in regions lacking NGS capabilities." (PMID 40433050, 2025). "Additionally, genetic mutations, including BRCA2, BCL6, CHEK2, and others, were also considered valuable predictors of BCR in prostate cancer." (PMID 40660132, 2025). "Consistent with BRCA2 and ATM showing association with disease severity, their effect sizes were larger in this aggressive prostate cancer versus controls analysis compared to the overall prostate cancer versus controls analysis." (PMID 39971927, 2025). "The SIR of prostate cancer was 7.8 (95CI: 5.3‒11, P < 0.001), 5.5 (95CI: 2.9‒9.4, P < 0.001), and 11 (95CI: 6.6‒17, P < 0.001) for men, men with an LP/P BRCA1 variant, and men with an LP/P BRCA2 variant, respectively." (PMID 39838196, 2025). "BRCA2 and BRCA1 variants are associated with hereditary predisposition to prostate cancer." (PMID 38996041, 2025). "Pathogenic variants (PVs) in BRCA2 are a major cause of hereditary breast and ovarian cancer (HBOC) syndrome, a condition characterized by a significantly increased risk of developing breast, ovarian, pancreatic, and prostate cancers." (PMID 40462315, 2025). "For instance, prostate cancer with mutations in homologous recombination repair genes such as BRCA1 and BRCA2 shows increased sensitivity to poly (ADP-ribose) polymerase (PARP) inhibitors and may benefit from platinum chemotherapy." (PMID 40027043, 2025). "Furthermore, mutations in DNA damage repair genes such as BRCA2, ATM, CHEK2, BRCA1, RAD51, and PALB2 have been implicated in familial prostate cancer." (PMID 40716035, 2025). "Moreover, studies in ovarian and prostate cancer have revealed multiple-gene (e.g., BRCA1 and BRCA2) reversion mutations merely identified in progressive tumor tissues, which lead to the restoration of DNA repair function and acquired drug resistance." (PMID 39104720, 2024). "Next, we further analyzed whether AURKB mRNA levels affect the prognosis of prostate cancer patients depending on BRCA2 status." (PMID 37934606, 2024). "Therefore, our observations suggest that patients carrying a PV in BRCA2 plus another HR gene should be carefully monitored for BC, pancreatic cancer, and prostate cancer." (PMID 38929805, 2024). "SAC inactivation is common in BRCA2-deficient prostate cancer patients, but PP2A inhibitors could reactivate the SAC and achieve BRCA2-deficient prostate tumor synthetic lethality." (PMID 37934606, 2024). "Similar to ENOC, in prostate cancer, RB1 loss is associated with poorer survival: early somatic co-deletion of BRCA2 and RB1 is associated with an aggressive, castration-resistant prostate cancer subtype characterized by epithelial-to-mesenchymal transition and shorter survival." (PMID 38837893, 2024).
prostate carcinoma (continued). "Research on BRCA2 carriers has demonstrated a correlation between the presence of BRCA2 and an increased incidence of prostate cancer, a younger age at diagnosis, a higher prevalence of clinically significant prostate cancer, and a more aggressive disease course." (PMID 39364320, 2024). "Additionally, the research demonstrated that PARPis Olaparib and Talazoparib significantly hamper the growth of prostate cancer cell lines and organoids derived from human mCRPC exhibiting both homozygous and heterozygous co-deletion of BRCA2 and RB1." (PMID 38672640, 2024). "Subsequently, other PARP inhibitors combination Talazoparib + Enzalutamide, Niraparib + Abiraterone Acetate + Prednisone, were approved in 2023 for treating patients with metastatic castration-resistant prostate cancer with alterations in BRCA1, BRCA2, and HRR deficiency gene mutation." (PMID 39175508, 2024). "Although there have been previous case reports of concurrent breast and prostate cancer, it appears that there have been no reports of concurrent two cancers due to BRCA2 gene mutations." (PMID 39364320, 2024). "Prostate cancer susceptibility is influenced by the BRCA1 and BRCA2 genes." (PMID 39132508, 2024). "Notably, BRCA2 has emerged for its clinical relevance in the treatment and screening of prostate cancer." (PMID 37345060, 2023). "No tools account for prostate cancer-specific features or can simultaneously identify BRCA2 deficient (BRCA2d), CDK12 deficient (CDK12d), and MMRd mCRPC from individual patient samples." (PMID 36914848, 2023). "A pathogenetically significant BRCA2 mutation c.8673_8674delAA was identified only in prostate cancer patients without an aggressive course of this disease." (PMID 37628606, 2023). "In addition, male relatives of BRCA2 carriers have increased risks for pancreatic and prostate cancers." (PMID 36861435, 2023). "For example, the HRD scores of patients with prostate cancer were significantly lower than those of patients with ovarian cancer, and the HRD scores of patients with prostate cancer and BRCA2 mutations were significantly higher than those of patients with ATM and CHEK2 mutations." (PMID 36791952, 2023). "The distribution of these variants (BRCA1 vs. BRCA2) in Ashkenazi men with prostate cancer is not clear." (PMID 36612302, 2023). "We examined the aggregate association of rare germline pathogenic/likely pathogenic/deleterious (P/LP/D) variants in ATM, BRCA2, PALB2, and NBN with a polygenic risk score (PRS) on prostate cancer risk among 1,796 prostate cancer cases (222 metastatic) and 1,424 controls of African ancestry." (PMID 38014910, 2023). "Among them, in BRCA2 mutation carriers, the relative risk of developing prostate cancer by 65 years of age is 7.33-times higher than in non-carriers." (PMID 37828628, 2023). "Germline mutations and somatic mutations in BRCA1 and BRCA2 gene mutations account for approximately 6–7% each in prostate cancer; however, they do not strongly affect PSA values." (PMID 37848957, 2023). "Finally, germline PVs in BRCA1, BRCA2, PALB2 or ATM were independently associated with short time to castration in patients with advanced prostate cancer." (PMID 37511593, 2023). "PALB2 is a protein that interacts with BRCA2 and is closely related to familial prostate cancer." (PMID 37298192, 2023). "BRCA2 pathogenic variants carriers have 44.0, 3.69, 3.34 and 2.22-fold elevated lifetime risk of the male breast, stomach, pancreatic and prostate cancers compared to non-carriers, respectively." (PMID 36439508, 2022).
prostate carcinoma (continued). "Finally, we performed a meta-analysis comparing the effects of BRCA2m on OS in prostate cancer patients, which suggested that prostate patients with BRCA2m had worse OS than BRCA2 wt (HR: 1.85 (95% CI = 1.07–3.21))." (PMID 35909902, 2022). "In the case of ovarian and prostate cancers, their classification as homologous recombination repair (HRR) deficient (HRD) or mutated also makes PARPi an available treatment option beyond BRCA1 or BRCA2 mutational status." (PMID 36969741, 2022). "Our findings speculate that BRCA2-altered prostate cancer progresses rapidly to metastatic and castration-resistant disease not necessarily accompanied by increased serum PSA level." (PMID 36362213, 2022). "In a study of 6500 patients with BRCA1 and BRCA2 PVs, c.756-c 1000 and c.7914þ regions in BRCA2 were reported as negative biomarkers for high risk of Gleason 8b prostate cancer." (PMID 36010882, 2022). "Prostate cancers with germline BRCA1 or BRCA2 mutations tend to be more aggressive than those without these mutations." (PMID 36551924, 2022). "Prostate cancer is dominated by BRCA2 prevalence at 9.6%, while BRCA1 has only 1.2%." (PMID 34979999, 2022). "Using the WGS data, we assessed the presence of variants and/or mutations in several genes that are known to be frequently mutated in prostate cancer (BRCA1, BRCA2, RB, PTEN, CDK12, PI3K, ADP-ribose, PIK3GA, PIK3CB and PIK3R1, AKT, CYP17, IGF 1, EGF, and BCL2)." (PMID 36643868, 2022). "Between 5-10% of BCs are attributed to inherited genetic variations mainly in two high-risk genes, BRCA1 and BRCA2, associated to the hereditary breast and ovarian cancer syndrome (HBOC), which confer a high risk of breast, ovarian, pancreatic and prostate cancer." (PMID 36119527, 2022). "The PRSER+ and PRSPC odds ratios with breast or prostate cancer risks appeared to be larger for class II variant (pathogenic variants likely to yield stable mutant proteins) carriers compared with class I BRCA1 and BRCA2 variant carriers." (PMID 34320204, 2022). "Indeed, in the context of the IMPACT study, BRCA2 P/LPV carriers (n = 902) had a higher incidence of prostate cancer, younger age of diagnosis, and clinically significant tumors compared with non-carriers (n = 497)." (PMID 36230512, 2022). "In prostate cancer, BRCA1/2 mutations represent around 13% of the of DDR genes alterations in tumor samples and 51% of all germline variants found in individuals affected by prostate cancer, with BRCA2 harboring the majority of variants." (PMID 35563100, 2022). "The associations of BRCA1/2 PVs with the risks of male breast and pancreatic cancers were confirmed and refined, as well as the association of prostate cancer with BRCA2 PVs, regardless of age and aggressiveness." (PMID 35077220, 2022). "In addition, five prostate cancer–associated genes (EGF, PIK3R1, ATM, BRCA1, and BRCA2) with apparent damaging mutations, one of which is a rare mutation in ATM, a possible therapeutic target, further support this claim." (PMID 36643868, 2022). "In an attempt to better understand the impact of BRCA2 mutations on the immune phenotype of prostate cancer, Jenzer and colleagues performed immunohistochemistry and T-cell receptor (TCR) sequencing in nine BRCA2-mutated and nine BRCA wild-type, hormone-sensitive prostate cancers." (PMID 34067105, 2021). "In the BRCA2 gene, a prostate cancer cluster region (PCCR) has been identified, in which the oligonucleotide/oligosaccharide- binding domain 1 (OB1) and Tower domain 2 (OB2) correlated with the highest risk of prostate cancer." (PMID 34884434, 2021).